TLR4 (toll like receptor 4)
Diseases named in the same sentence as TLR4 in open-access papers (continued):
Sharing a sentence is not in itself a finding about the gene and the disease.
melanoma (continued). "In summary, the results of this study suggested that TLR4 may be a ligand of PA, promoting the lung metastasis of melanomas by triggering downstream TRIF-Peli1-pNF-κB to induce cell migration and invasion." (PMID 36422271, 2022). "TLR4 seemed to play an important role in the proliferation and invasion of the melanoma cells." (PMID 36422271, 2022). "In addition, the UV-induced activation of TLR4 promotes the inflammatory production of neutrophils as well as the angiogenesis and metastasis of melanomas." (PMID 36422271, 2022). "Furthermore, hsa-miR-145-5p overexpression inactivated the NF-κB pathway in melanoma in vitro and in vivo, which was reversed by TLR4 overexpression, suggesting that miR-145-5p hindered the occurrence and metastasis of melanoma cells." (PMID 34149728, 2021). "It has also been shown that LMW hyaluronan promotes melanoma lymph node metastasis, soluble LMW hyaluronan contributes to melanoma cell proliferation, and shorter hyaluronan fragments induce TLR4-mediated signaling in melanoma and promote inflammation as well as invasiveness." (PMID 35127523, 2021). "Particularly, it has been suggested that TLR4 may contribute to melanoma progression and migration and that FSCN1 promotes EMT events." (PMID 33916029, 2021). "Also, hsa-miR-145-5p inhibits tumor occurrence and metastasis through the NF‐κB signaling pathway by targeting TLR4 in malignant melanoma." (PMID 34149728, 2021). "Furthermore, melanoma-derived extracellular vesicles carrying heat shock protein (HSP)-86 can stimulate PD-L1 expression in myeloid cells via TLR4 signaling." (PMID 34829995, 2021). "Meanwhile, hsa-miR-145-5p restrained melanoma tumor growth in vivo by targeting TLR4." (PMID 34149728, 2021). "Moreover, TLR4 overexpression abolished the inhibition of cell proliferation, colony formation, migration, and invasion abilities induced by hsa-miR-145-5p in melanoma cells." (PMID 34149728, 2021). "Also, UV-induced neutrophilic inflammatory response, including the release of high mobility group box 1 (HMGB1) and Toll-like receptor 4 (TLR4), promoted angiogenesis and metastasis in melanoma cells." (PMID 32630437, 2020). "Next we examined whether activation of STAT3 is required for TLR4 signaling-mediated melanoma progression in vivo." (PMID 32312954, 2020). "Next, we examined whether inhibiting the TLR4/STAT3 pathway suppresses proliferation of melanoma cells in vitro and in vivo." (PMID 32312954, 2020). "We have shown that STAT3 activation is important for TLR4 signaling-mediated melanoma progression." (PMID 32312954, 2020). "TLR4 is expressed in 90% of human primary melanoma lesions and 93% of metastatic lesions." (PMID 32312954, 2020). "In conclusion, activation of STAT3 is a key event in TLR4 signaling-mediated melanoma progression." (PMID 32312954, 2020). "Next, we examined whether activation of STAT3 is required for the cellular events in TLR4 signaling-mediated melanoma progression." (PMID 32312954, 2020). "Moreover, HMGB1 facilitated ALO mediated melanoma cell apoptosis by binding to its receptor, Toll-like receptor 4 and activating extracellular regulated protein kinases (ERK) signal pathway." (PMID 32536835, 2020). "These facts together substantiate that TLR4 signaling promotes melanoma development." (PMID 32312954, 2020). "Consistently, we have demonstrated that dedifferentiated melanoma cells express inflammation-related genes such as pentraxin 3 (PTX3), which contribute to melanoma invasiveness and the mesenchymal-resistant phenotype via a Toll-like receptor 4 (TLR4)-NF-κB-TWIST pathway." (PMID 32466585, 2020). "However, signal transduction mediated by TLR4 for driving melanoma progression is not fully understood." (PMID 32312954, 2020). "We therefore speculate that there is a TLR4/STAT3/PU.1 positive feedback loop in melanoma, which leads to the high expression of TLR4 and constitutive activation of STAT3." (PMID 32312954, 2020).
melanoma (continued). "Moreover, in a mouse model, we demonstrated that STAT3 activation is required for TLR4 signaling-promoted melanoma progression in mice." (PMID 32312954, 2020). "Further studies are required for establishing the TLR4/STAT3/PU.1 loop in melanoma." (PMID 32312954, 2020). "Moreover, treatment of B16F10 cells with TLR4 inhibitor prior treatment with pioglitazone indicate that the anticancer effects of pioglitazone on melanoma cells was dependent on TLR4." (PMID 32665906, 2020). "For other SNPs of TLR4, rs1927914 affects the risk of various tumors, including liver cancer, prostate cancer, gastric cancer, and malignant melanoma but not the risk of hepatocellular carcinoma." (PMID 32351566, 2020). "Researchers have also found that polyphenols from tea could significantly suppress proliferation, migration, and invasion in melanoma by TLR4 inhibition." (PMID 30863401, 2019). "TP could suppress TLR4expression both in normal melanomas and in stimulated melanomas by TLR4 agonistLPS." (PMID 29359608, 2018). "Suppressing TLR4 in melanomas could inhibit cell function (proliferation,migration, and invasion), and blocking the expression of 67LR could abolish TPfunction on TLR4." (PMID 29359608, 2018). "In support to these findings, TLR4-mediated signaling was activated in PTX-resistant melanoma cells and the interfering of this pathway could reverse PTX resistance." (PMID 29486738, 2018). "As compared with normal skin cells, TLR4 was greatly expressed in melanoma cells." (PMID 30585192, 2018). "Italso investigated TP/TLR4 connection and their co-function on melanoma cells.Through the mechanism study, we may enlighten future melanoma therapy." (PMID 29359608, 2018). "However, it is of interest to note that both melanoma cells and tumor-infiltrating macrophages can express TLR4, which was recently identified as the eNAMPT receptor." (PMID 29721178, 2018). "The evidences in melanoma cells has been reported that TLR4-MyD88-ERK signaling may be a novel target for reversing chemoresistance to PTX." (PMID 29486738, 2018). "Interestingly, protein ligands S100A8 and S100A9 and cognate receptor TLR4 were all identified in melanoma EV cargo." (PMID 28424693, 2017). "Data from our laboratory demonstrated that Icariside II enhanced paclitaxel-induced apoptosis in human melanoma cells, which might be due to its inhibition on paclitaxel-induced activation of TLR4-MyD88-ERK signaling." (PMID 27649234, 2016). "In a recent study, a specific role of TLR-4 in the process of melanoma cells growth was reported." (PMID 26395996, 2016). "Our data showed that icariside II treatment could effectively inhibit paclitaxel-induced activation of TLR4-MyD88-ERK signaling pathway in human melanoma A375 cells, which is proposed to be a novel target for reversing chemoresistance to paclitaxel." (PMID 27649234, 2016). "In this work we study the effect induced by BLS in TLR4-expressing B16 melanoma." (PMID 25973756, 2015). "A similar mechanism may be responsible for the decreased expression of TLR4 observed in BLS-stimulated melanoma cells in vitro." (PMID 25973756, 2015). "For instance, autologous DCs electroporated with mRNA encoding CD40L (plus CD70 and TLR4) and fusion protein of an HLA class II-targeting signal (DC-LAMP) and melanoma-associated antigens (TriMixDC-MEL) were immunogenic and generated tumor responses in chemorefractory melanoma." (PMID 26082780, 2015). "The variant allele of TLR4-rs2149356, exhibited association with decreased risk of melanoma that was not statistically significant." (PMID 21931695, 2011). "Using a mouse model of melanoma metastasis induced by intravenous injection of B16-F10 cells, we investigated the mechanism responsible for the diverse efficacy of the prophylactic or therapeutic TLR4 and TLR9 agonist complex against metastasis." (PMID 21931823, 2011).
melanoma (continued). "Toll-like receptor 4 and other TLRs have been detected in many murine and human cancer cell lines, including laryngeal, lung, breast, gastric, colon, prostate cancer, and melanoma." (PMID 20145615, 2010). "The commensal microbial community could also positively affect patient’s outcomes through activating CD8+ T cells-dependent antitumor response, enhancing antitumor T cell immunity by activating DCs via toll-like receptor 4 (TLR4) signaling in melanoma mice receiving radiation." (PMID 40124706, 2024). "In addition, knocking out TLR4 can significantly reduce melanoma metastasis." (PMID 36422271, 2022). "In addition to MYD88 and TRIF, other molecules might be involved in the signaling cascades from TLR4 to STAT3 in melanoma." (PMID 32312954, 2020). "TLR4 protein expression level in melanoma was high expressed and it couldbe down-regulated by TP." (PMID 29359608, 2018). "TLR4 inhibition could significantly suppressproliferation, migration, and invasion in melanoma." (PMID 29359608, 2018). "In melanoma, increased expression of the TLR4 agonist HMGB1 enhances the proliferation of tumor cells, but its correlation with patient survival and melanoma progression is low." (PMID 40969278, 2025). "LPS potently activates the toll-like receptor 4 (TLR4), which is activated in TAMs and other cells within tumors and plays a key role in modulating TME, including in melanoma." (PMID 40867314, 2025). "Melanoma-derived EVs, by incorporating inducible heat shock protein 86 (HSP86), activate TLR4 on myeloid cells, which in turn activates NF-κB to upregulate the expression of PD-L1." (PMID 40443670, 2025). "For instance, the co-expression of CD40L with GM-CSF in bystander cells and with toll-like receptor 4 (TLR4)/CD70 or TLR4/CD70/tumor antigen in autologous DCs was employed for the treatment of advanced lung adenocarcinoma and advanced melanoma." (PMID 39120299, 2024). "To date, no clinical trial targeting TLR4 in HCC is ongoing, while the TLR4 agonist GLA-SE has been tested for the treatment of advanced soft-tissue sarcoma (NCT02180698, Phase I) and stage II-IV melanoma (NCT02320305, Early Phase I)." (PMID 38473265, 2024). "In experiments involving melanoma cells, PTX3 was found to interact with inflammatory signaling pathways, such as the TLR4 and NF-κB pathways." (PMID 39594709, 2024). "Melanoma can also release heat shock protein 86, acting as a DAMP, which is recognized by TLR4 on MDSCs." (PMID 36911674, 2023). "PTX3, a key factor in a subtype of invasive melanoma, can mediate the expression of the EMT transcription factor TWIST1 through a TLR4/MYD88/IKK/NF-κB signaling pathway and drive melanoma cell migration." (PMID 37277447, 2023). "For instance, EVs derived from human melanoma cell lines have been found to inhibit dendritic cell (DC) maturation via S100A8 and S100A9 proteins, which signal via TLR4, among others." (PMID 36081494, 2022). "It has been reported that this product inhibits pulmonary metastasis in mice inoculated with B16 melanoma (a murine tumor cell line used for research as a model for human skin cancers) by regulating the HMGB1/RAGE and HMGB1/TLR4 signal transduction pathways." (PMID 36012593, 2022). "From MetaCore network analysis, three hub genes (TLR4, ITGA6, and BTG2) were identified as targeted by multiple miRNAs, either up- or downregulated in multiple melanomas." (PMID 33980826, 2021). "MMP2 expression in melanoma promotes tumor growth in a TLR2- and TLR4-dependent manner that requires APCs and T cells." (PMID 34032639, 2021). "To determine the correlation of TLR4 expression and STAT3 activation/phosphorylation, we took advantage of the human melanoma tissue microarray (a total of 208 samples) and performed immunohistochemical staining." (PMID 32312954, 2020). "First, we found that TLR4 expression and STAT3 activation are positively correlated in human melanoma tissues." (PMID 32312954, 2020).
melanoma (continued). "Parthenolide also downregulates protein levels of TLR4, STAT3 and phosphorylated STAT3 in tumor tissues and impedes tumor growth in melanoma-bearing mice." (PMID 32312954, 2020). "Further analyses showed that TLR4 expression and STAT3 phosphorylation were positively correlated in the 208 samples, especially in early-stage (T1N0M0) melanomas (samples C4, D9, F2, F9, G9, H8, H9)." (PMID 32312954, 2020). "SSSRs encompass Extracellular Matrix Metalloproteinase Inducer (EMMPRIN), Activated Leukocyte Cell Adhesion Molecule (ALCAM), Toll-like Receptor 4 (TLR-4), Neuroplastin (NPTN) β, and Melanoma Cells Adhesion Molecule (MCAM)." (PMID 33256110, 2020). "In this study, we demonstrated that activation of TLR4/MYD88/STAT3 and TLR4/TRIF/STAT3 pathways promotes proliferation of cultured melanoma cells." (PMID 32312954, 2020). "In this study, we found that knockdown of TLR4 not only inhibits STAT3 activation, but also induces STAT3 protein degradation, suggesting an alternative approach to blocking STAT3 signaling in melanoma: genetically or pharmacologically inhibiting TLR4." (PMID 32312954, 2020). "Results showed that both parthenolide and TAK-242 dose-dependently lowered protein levels of TLR4, STAT3 and phosphorylated STAT3 in and inhibited the proliferation of A375 and B16 melanoma cells." (PMID 32312954, 2020). "It was found that protein level of phosphorylated STAT3 and transcriptional activity of STAT3 were higher in A375CA-TLR4 cells than in A375NC cells, indicating that constitutive activation of TLR4 enhances STAT3 activation in melanoma cells." (PMID 32312954, 2020). "TLR4 signaling activates STAT3 through MYD88 and TRIF, and subsequently upregulates a series of STAT3 target genes to promote melanoma progression." (PMID 32312954, 2020). "Protein levels of TLR4 and phosphorylated STAT3 (Y705) were significantly elevated in melanoma tissues compared to that in normal tissues, a finding consistent with previous reports." (PMID 32312954, 2020). "Collectively, the positive correlation together with the high levels of TLR4 expression and STAT3 phosphorylation in human melanoma tissues suggests a link between TLR4 and STAT3 in melanoma pathogenesis." (PMID 32312954, 2020). "In the tissue microarray analyses, we found that TLR4 expression and STAT3 phosphorylation are positively correlated in melanoma tissues." (PMID 32312954, 2020). "The TLR4/MYD88/STAT3 and TLR4/TRIF/STAT3 pathways established in this study shed novel insights into the pathophysiology of melanoma, and suggest new, potentially more effective, targets for treating melanoma." (PMID 32312954, 2020). "Using cancer vaccines or adoptively transferred T cells, we demonstrate here that the tumor-killing efficacy of CD8 T cells against established melanoma and glioblastoma tumors can be greatly enhanced by modulating the TME with a potent synthetic TLR4 agonist." (PMID 32579133, 2020). "A recent study also showed that HMGB1 released from UV-damaged keratinocytes activates TLR4/MYD88-dependent neutrophilic inflammation, which can promote angiotropism and metastasis of melanoma cells." (PMID 29636841, 2018). "This study aims to explore the effect of TLR4 in PTX resistance in triple-negative BCA and advanced melanoma and the effect of compound A (CpdA) to attenuate this resistance." (PMID 29486738, 2018). "This is in contrast with what has been found by others, e.g., co-administration of IMQ and anti-CD40 is ineffective against intradermal B16 melanomas, and required a combination of TLR3, TLR4 and TLR7 stimulation to produce 50% tumor rejection." (PMID 25518732, 2014). "In virtue of their TLR expression, B16 melanoma cells were found to respond to ligands to TLR3 and TLR4 by releasing substantial levels of IFN-I that induced DC activation and resulted in tumor growth inhibition by the host." (PMID 24400008, 2013).
melanoma (continued). "Cancer cells from other sites (e.g., melanoma, breast) have been shown to express TLR2, and TLR4 expression has been noted on tumour cells in head and neck squamous cell carcinoma." (PMID 21179035, 2011). "Melanoma-derived PTX3 promotes cancer cell invasion and migration via TLR4/NF-κB signaling pathway." (PMID 41479916, 2025). "Additionally, melanoma-derived EVs enriched with HSP72 and HSP105 activate TLR2 and TLR4 on DCs to promote IL-6 production." (PMID 40908470, 2025). "Moreover, dual immunofluorescence analysis of microglial expression of a DAMP response marker, TLR4, showed elevated TLR4-IBA1 immunoreactivity (29–60% increase) in the melanoma + vehicle and combi-ICI-treated groups." (PMID 40605058, 2025). "For example, TLR4, RAGE, and EMMPRIN were reported to be expressed in metastatic melanoma cells, and the EMMPRIN-mediated stimulation of melanoma cells with the extracellular S100A8/A9 secreted from the lung strongly facilitated the remote metastasis of melanoma cells to the lung." (PMID 36142212, 2022). "The ER stress of three different murine cancer cell lines, including prostate cancer TRAMP-C1, melanoma B16F10, and Lewis lung carcinoma (LLC), could promote proinflammatory responses of macrophages through Toll-like receptor 4 (TLR4) signaling." (PMID 35372022, 2022). "TLR4 activation leads to NF-κB-mediated signaling and production of inflammatory cytokines and chemokines such as IL-6, IL-8, CXCL-1 and CXCL-10 in melanocytes and IL-8 and MMP-2 secretion in melanoma cells." (PMID 35127523, 2021). "In addition, CpdA dramatically attenuated TLR4-induced IL-6, IL-8 and XIAP expressions in both MDA-MB-231 BCA and MDA-MB-435 melanoma cells compared to cells with only PTX treatment." (PMID 29486738, 2018). "This study aims to explore role of TLR4 in PTX resistance of triple-negative BCA and melanoma." (PMID 29486738, 2018). "In the present study, it was extensively demonstrated that PTX induced pro-inflammatory mediators and tumor survival via TLR4 signaling pathway and CpdA could inhibit this pathway and attenuate the resistance of PTX in BCA and melanoma cells." (PMID 29486738, 2018). "CpdA can target this pathway and attenuate TLR4-mediated PTX resistance in BCA and melanoma; hence, combination treatment with PTX and CpdA may be considered not only to sensitize cancer cells to PTX, but also to prevent PTX resistance." (PMID 29486738, 2018). "In conclusion, the possible impact of TLR4-dependent signaling pathway in PTX resistance in BCA and melanoma is proposed and using PTX in combination with CpdA may attenuate TLR4-mediated PTX resistance in the treatment of the patients." (PMID 29486738, 2018). "Our study suggests that zymosan-induced upregulation of TLR-2, TLR-4 and TNF-α gene expression and of TNF-α release; together with increased level of lymphocyte proliferation may play a role in the inhibition of melanoma progression." (PMID 29588627, 2018). "The relationship among TP, TLR4, and melanoma had never been discussed before, whichwas the novel point in this research." (PMID 29359608, 2018). "Although some cancer cells like melanoma cells are known to respond to lipopolysaccharide (LPS) via TLR4, not all cancer cells are positive for TLR4." (PMID 17156435, 2006). "Moreover, extracellular IFI16 promotes TLR4‐mediated inflammation via LPS binding, sustains STING expression to activate IFN‐γ signaling in melanoma, and exerts antitumor effects by inducing apoptosis, inhibiting neovascularization, and enhancing macrophage recruitment." (PMID 41316520, 2025). "Furthermore, we established a subcutaneous B16-F10 melanoma model for intratumoral BCG treatment and compared wild type mice to TLR2-/-, TLR3-/-, TLR4-/-, TLR7-/-, TLR3/7/9-/-, caspase 1-/-, caspase 11-/-, IL-1R-/-, cGAS-/-, STING-/-, IFNAR-/-, MyD88-/-deficient animals." (PMID 38835781, 2024). "In addition, we found that knockdown of TLR4 lowered the protein level but not the mRNA level of STAT3 in melanoma cells." (PMID 32312954, 2020).